ATF6 (activating transcription factor 6)
Diseases named in the same sentence as ATF6 in open-access papers (continued):
Sharing a sentence is not in itself a finding about the gene and the disease.
leukemia (7 papers, 2015 to 2026). A malignant (clonal) hematologic disorder, involving hematopoietic stem cells and characterized by the presence of primitive or atypical myeloid or lymphoid cells in the bone marrow and the blood. "For example, as one of the three major effectors of UPR, ATF6α activation plays a vital role in conferring imatinib resistance on leukemia cells, which is regulated by protein disulfide isomerase A5 (PDIA5)." (PMID 30413206, 2018). "Although the role of ATF6 in tumorigenesis remains elusive, it was recently demonstrated that upregulated ATF6 in leukemia cells confers resistance to imatinib and depletion of ATF6 restores sensitivity to imatinib." (PMID 30282948, 2018). "The detailed mechanism for ATF6 activation and ATF6 induced imatinib resistance in leukemia has been described." (PMID 26622781, 2015). "Furthermore, silencing of ATF6 expression sensitized K562R cells (a leukemia cell line resistance to imatinib) to the treatment of imatinib." (PMID 26622781, 2015).
lung fibrosis (7 papers, 2013 to 2025). "Some of the compounds we used to target these pathways (i.e. STF-083010 and KIRA8 against IRE1α and AEBSF against ATF6) have been extensively used in preclinical studies for neurodegenerative diseases, autoimmune diabetes, cancer and pulmonary fibrosis." (PMID 34138976, 2021). "Here, we investigated whether ER stress contributes to lung fibrosis following MERS-CoV infection by analyzing the levels of ER-stress-associated genes, such as Perk, Atf4, Chop, Atf6, and X-box binding protein 1 (Xbp1) in the lungs of MERS-CoV-infected hDPP4-Tg mice and sham-infected hDPP4-Tg mice." (PMID 33139653, 2020). "In a lung fibrosis model, mice following bleomycin treatment also demonstrated activation of ER stress genes, ATF4 and ATF6, in the distal airway and honeycomb cysts." (PMID 37978501, 2023). "ER stress transducers, such as ATF6 and CHOP, are known to play a prominent role in apoptosis of alveolar type II epithelial cells in fibrotic lung diseases, such as Idiopathic Pulmonary Fibrosis (IPF) and Hermansky Pudlak Syndrome (HPS)." (PMID 24364984, 2013).
Parkinson disease (7 papers, 2012 to 2025). A progressive degenerative disorder of the central nervous system characterized by loss of dopamine producing neurons in the substantia nigra and the presence of Lewy bodies in the substantia nigra and locus coeruleus. "It has been shown that the accumulation of α-synuclein (α-syn), a hallmark of Parkinson's disease (PD), inhibits the Unfolded Protein Response (UPR) pathway, particularly the ATF6 branch, which is crucial for cell survival." (PMID 40552310, 2025). "In Parkinson’s disease studies, the activation of UPR maintains the protein homeostasis in ATF6-deficient mice." (PMID 30241539, 2018). "However, similar changes in ATF6 and CASP3 gene expression are also observed in Parkinson's disease patients’ DNs." (PMID 27536002, 2016). "Recombinant CDNF protein has been shown to reduce levels of the Atf6 UPR transcript in thapsigargin-treated embryonic mouse dopamine neurons in vitro and the level of GRP78 protein and ATF6 transcripts in the rat striatum in a 6-OHDA model of Parkinson’s disease in vivo." (PMID 36012764, 2022).
heart failure (6 papers, 2019 to 2023). Inability of the heart to pump blood at an adequate rate to meet tissue metabolic requirements. "ATF6α roles have been implicated in adipogenesis, neural and muscular embryogenesis, retina development, foveal disease and heart failure, among others." (PMID 37025177, 2023). "Like ATF6, Xbp1s deficient mice display a worse recovery from heart failure showing an increased infarct size while in vivo overexpression of this gene is translated into reduced infarct size after I/R injury." (PMID 37373035, 2023). "Moreover, Atf6 or Atf6b null mice, and Atf6+/−Atf6b+/− double heterozygous targeted mice each showed accelerated decompensation and heart failure after long-term (8 week) pressure overload stimulation." (PMID 30765833, 2019). "However, we were able to generate double heterozygous mice (Atf6+/−Atf6b+/−) and they showed the same increased propensity to heart failure as either single null line after 8 weeks of TAC." (PMID 30765833, 2019). "In coordination, lead candidate direct small molecule activators of ATF6 would be identified and validated for efficacy in small and large animal models of CVD and heart failure." (PMID 32138230, 2020). "Persistent ER stress–induced heart failure in AXER-KO medaka was well rescued by the constitutive expression of XBP1(S) but not of ATF6α(N), allowing AXER-KO XBP1 SC/+ medaka to live 3 d longer after hatching." (PMID 37160311, 2023). "Unlike PERK, ATF6 is involved in the progression of cardiac hypertrophy and heart failure response thus exerting a harmful role." (PMID 37373035, 2023). "Importantly, constitutive activation of IRE1α signaling—but not ATF6α signaling—rescued this heart failure and allowed AXER-KO medaka to survive 3 d longer, likely because of XBP1-mediated transcriptional induction of ER-associated degradation components." (PMID 37160311, 2023). "Unlike IRE1 or ATF6, PERK deficiency has a beneficial phenotype after heart failure displaying protection against pressure overload myocardial infarction suggesting that while ATF6 and IRE1 exert a protective role against heart failure, PERK and its downstream pathways are detrimental." (PMID 37373035, 2023).
Huntington disease (6 papers, 2018 to 2023). Huntington disease (HD) is a rare neurodegenerative disorder of the central nervous system characterized by unwanted choreatic movements, behavioral and psychiatric disturbances and dementia. "In 2016, we reported that RP competes with the DREAM–ATF6 interaction, increasing ATF6 processing and promoting neuroprotection in a mouse model of Huntington’s disease." (PMID 37958767, 2023). "Modulation of the ATF6–DREAM interaction with repaglinide (RP) induced neuroprotection in a model of Huntington’s disease." (PMID 37958767, 2023). "Downregulation of DREAM is part of an endogenous neuroprotective mechanism that improves ATF6 (activating transcription factor 6) processing, neuronal survival in the striatum, and motor coordination in R6/2 mice, a model of Huntington’s disease (HD)." (PMID 29523177, 2018). "The abnormal expression of ATF6 is implicated in diseases such as ALS and Huntington’s disease." (PMID 37376599, 2023).
osteosarcoma (6 papers, 2018 to 2024). A usually aggressive malignant bone-forming mesenchymal neoplasm, predominantly affecting adolescents and young adults. "In relapsed/refractory osteosarcoma (OS), ATF6α cleavage and activity were enhanced in OS cells compared to normal osteoblasts, and knockdown of ATF6α expression sensitized OS cells to chemotherapeutic drugs and induced cell death by activating Bax." (PMID 38297380, 2024). "In osteosarcoma, upregulation of ATF6 and E2F7 during sustained ERS suppressed E2F1 expression, upregulation of E2F7 was dependent on activation of XBP1, and downregulation of E2F1 enhanced Noxa and Puma expression and promoted ER stress-induced apoptosis." (PMID 36551309, 2022). "Studies have shown that ATF6α activation is an indicator of poor prognosis in osteosarcoma and improves cell survival after chemotherapy." (PMID 36551309, 2022). "Endoplasmic reticulum (ER) stress markers BiP, CHOP, ATF4 and ATF6 were induced in osteosarcoma cells." (PMID 30250645, 2018). "The expression levels of UPR markers (IRE1, PERK, and ATF6) were detected by western blotting to determine whether α-linolenic acid induced ER stress in osteosarcoma MG63 and 143B cells." (PMID 35566090, 2022). "However, there are still some limitations in the present study, in vivo studies are needed to clarify osteosarcoma cell apoptosis and proliferation caused by CENPF resulting from XBP1 and ATF6 signaling pathway." (PMID 32973403, 2020). "Under ERS, ATF6 is activated and binds to the PLK4 promoter to recruit C/EBPβ, thereby inhibiting apoptosis in osteosarcoma cells." (PMID 36551309, 2022).
retinal degeneration (6 papers, 2014 to 2025). Degeneration of the retina. "Alternatively, deficiencies in ATF6 activation induced by environmental insults or aging contribute to retinal degeneration associated with other diseases including retinitis pigmentosa and cone-rod dystrophy." (PMID 37433773, 2023). "Our findings demonstrate that Atf6 is required for efficient clearance of rhodopsin protein in rod photoreceptors expressing P23H rhodopsin, and that loss of Atf6 ultimately accelerates retinal degeneration in P23H-KI mice." (PMID 34381136, 2021). "Our data demonstrate that by P60, loss of Atf6 accelerates retinal degeneration in Rho+/P23H mice." (PMID 34381136, 2021). "First, we examined steady-state levels of rhodopsin in retinal protein lysates collected from Atf6+/−Rho+/P23H and Atf6−/−Rho+/P23H at P12, an age before morphological defects in photoreceptors or retinal degeneration emerges in Rho+/P23H mice." (PMID 34381136, 2021). "We found increased retinal degeneration and diminished rhodopsin protein levels in P60 Atf6−/−Rho+/P23H retinas compared to P60 Atf6+/−Rho+/P23H." (PMID 34381136, 2021). "Why does loss of Atf6 increase retinal degeneration in Rho+/P23H mice at P60, while not affecting younger animals?" (PMID 34381136, 2021). "Ablation of CHOP, selective activation of ATF6 or PERK, disruption of CDK5 and MEKK1 pathway, or the stimulation of ERAD may serve as a powerful therapeutic strategy against rhodopsin mutants induced RP and reverse severe retinal degeneration." (PMID 25530840, 2014).
cone-rod dystrophy (5 papers, 2019 to 2025). Inherited retinal dystrophies that belong to the group of pigmentary retinopathies. "In patient P448, diagnosed with non-progressive cone-rod dystrophy at age 10, WES reanalysis identified a homozygous ATF6 c.160-8A>G variant with a strong genotype-phenotype correlation." (PMID 40926010, 2025).
Hypertension (5 papers, 2015 to 2025). The presence of chronic increased pressure in the systemic arterial system. "Of direct relevance to this review, targeted suppression of the ATF6 pathway has been demonstrated to ameliorate hypertension‐associated cardiac fibrotic remodelling and hemodynamic dysregulation, highlighting its central role in hypertensive end‐organ damage." (PMID 41360758, 2025). "Further analysis of the expression of THBS4, the cleaved form of ATF6α, and two of its targets by western blot confirmed the up-regulation of this pathway at the protein level in hypertension." (PMID 26356734, 2015).
liver disease (5 papers, 2014 to 2023). "In addition, previous research has shown that ATF6 has a protective and pathological role in certain liver disease models." (PMID 34778458, 2021). "Thus, investigating the mechanism of ATF6 influencing liver metabolism may be helpful for the liver disease treatment." (PMID 38007457, 2023). "The authors also showed the activation of UPR (ATF6, IRE1 and PERK) pathways in mild and advanced liver fibrosis, which is indicative of the presence of chronic ER-stress in advanced liver disease." (PMID 27223299, 2016). "They found high expression of GRP78 in the cytoplasm, nuclear translocation of activated ATF6, and spliced version of XBP mRNA, indicating that the presence of chronic ER-stress response in advanced liver disease." (PMID 27223299, 2016).
Multiple Myeloma (5 papers, 2011 to 2026). "ALMC-2 cells are a plasma cell line derived from a light chain amyloidosis patient, in which it has been shown that 147 activates the ATF6 arm of the UPR." (PMID 30084354, 2018). "In contrast, enhancing ATF6α activity using inducible activation of ATF6α-N increased quality control of protein folding in the ER and decreased secretion and extracellular aggregation of amyloidogenic proteins involved in light chain amyloidosis." (PMID 27435960, 2016).
non-small cell lung carcinoma (5 papers, 2021 to 2024). A group of at least three distinct histological types of lung cancer, including non-small cell squamous cell carcinoma, adenocarcinoma, and large cell carcinoma. "Current evidence suggests that ATF6α is associated with hepatocellular carcinoma, bladder cancer, non-small cell lung cancer (NSCLC) and prostate cancer." (PMID 38297380, 2024). "Research has shown that siRNA silencing of PERK or ATF6 can inhibit viral replication in NDV-infected human non-small-cell lung cancer (NSCLC) cell line A549 and SVV-infected BHK-21 cells." (PMID 39227990, 2024). "β-Elemene can upregulate the expression of the unfolded protein response-related proteins PERK, IRE1α and ATF6, increase ER stress, and ultimately promote non-small cell lung cancer (NSCLC) cell apoptosis." (PMID 39584140, 2024).
retinal disease (5 papers, 2015 to 2025). "If ATF6-targeting approaches prove effective in preserving vision and reducing neovascularization, they could lead to novel treatments for blinding retinal diseases." (PMID 41006433, 2025). "Taken together, our findings imply that the ATF6 pathway is essential in color vision not just within photoreceptors but also within the inner retina, and is a potential target for treatment for either inherited or acquired retinal diseases." (PMID 26063662, 2015).
Alzheimer disease (4 papers, 2017 to 2023). A progressive, neurodegenerative disease characterized by loss of function and death of nerve cells in several areas of the brain leading to loss of cognitive function such as memory and language. "In the Alzheimer’s disease pathway, we found genes up-regulated (Apbb1, Atf6, Cacna1d, Calm3, Casp7, Itpr1, Lpl, and Ppp3ca) and down-regulated (Aph1b, Bid, Cycs, Fadd, Fas, and Nae1)." (PMID 28513549, 2017).
amyloid disease (4 papers, 2016 to 2022). "This further highlights the potential for enhancing the activity of key ER quality control factors including BiP or PDIA4 through mechanisms such as ATF6 activation to ameliorate pathologic extracellular aggregation of TTR implicated in amyloid disease pathogenesis." (PMID 35626697, 2022). "Additional research shows that ATF6 transcription factor activation can attenuate amyloidosis through BACE1 downregulation, and concomitantly ATF6 overexpression significantly reduces Aβ1-42." (PMID 36561136, 2022). "A similar method has been used to investigate the molecular basis of activating transcription factor 6 (ATF6)-dependent regulation of immunoglobulin light-chain secretion in amyloidosis." (PMID 33581410, 2021). "However, classical amyloid diseases are associated with secretion of destabilized amyloidogenic proteins, and increasing the stringency of the ER quality control by activation of the UPR transcription factor ATF6 selectively decreases their secretion." (PMID 27926939, 2016). "Our results define a mechanistic basis to explain the ATF6 activation-dependent reduction in destabilized, amyloidogenic TTR secretion that could be therapeutically accessed to improve treatments of TTR-related amyloid diseases." (PMID 35626697, 2022).
cardiomyopathy (4 papers, 2022 to 2024). A disease of the heart muscle or myocardium proper. "Hence, these data suggest that Tbx20 directly binds to and induces the expression of atf6 during ER stress–mediated cardiomyopathy, thus maintaining the pool of atf6 during stressed conditions." (PMID 36805334, 2023). "In addition, we identify tbx20 as a direct target of Atf6 during ER stress–mediated cardiomyopathy." (PMID 36805334, 2023).
cataract (4 papers, 2015 to 2025). Partial or complete opacity of the crystalline lens of one or both eyes that decreases visual acuity and eventually results in blindness. "Our experimental data indicated that ATF6 was significantly up-regulated in cellular models of cataract disease." (PMID 40837408, 2025). "Compared with the normal controls, the ATF6 protein and mRNA levels in the lens of age-related and HM-related cataracts showed similar trends of substantial up-regulation." (PMID 26091066, 2015). "Finally, we sought to determine whether the ATF6 pathway was also activated in the lens of these three types of cataracts." (PMID 26091066, 2015). "However, the absence of cataracts in this single case does not definitively exclude ATF6's potential involvement in lens homeostasis." (PMID 40837408, 2025).
chronic pancreatitis (4 papers, 2019 to 2025). A chronic inflammatory process causing damage and fibrosis of the pancreatic parenchyma. "ATF6 serves as an inducer of genes that augment protein folding and restore protein homeostasis, while also promoting inflammation during the course of chronic pancreatitis." (PMID 38482016, 2024).
head and neck squamous cell carcinoma (4 papers, 2019 to 2025). A squamous cell carcinoma that arises from any of the following anatomic sites: lip and oral cavity, nasal cavity, paranasal sinuses, pharynx, larynx, and salivary glands. "The CERS6/C16-ceramide induces apoptosis in human head and neck squamous cell carcinoma by the endoplasmic ER-mediated ATF6/CHOP response pathway." (PMID 41203639, 2025). "Selective activation of ATF-6 in response to CERS6/C16 ceramide down-regulation protects head and neck squamous cell carcinoma cells from ER stress-induced apoptosis by preventing ER/Golgi [Ca2+] depletion and CHOP activation." (PMID 41203639, 2025). "However, the opposite effect could also be seen in head and neck squamous cell carcinoma where knockdown of CerS6 and depletion of its product C16:0-ceramide induced UPR and subsequent apoptosis through decreased ER Ca2+, fusion of the ER and Golgi, and activation of ATF6 signaling." (PMID 39608570, 2024).
hypothyroidism (4 papers, 2018 to 2024). Abnormally low levels of thyroid hormone. "First, we observed that hypothyroidism-induced endoplasmic reticulum stress in the third week after thyroidectomy because IRE1α, PERK, and ATF6α pathways are overactivated with a persistent proapoptotic state." (PMID 34295248, 2021). "Hypothyroidism increased apoptosis index, TBARS and LOOH concentrations, and reduced testicular gene expression of Sod1, Sod2 and Gpx1, as well as the expression of Grp78, Atf6, Ho1 and Chop." (PMID 38338793, 2024). "To probe that hypothyroidism may induce endoplasmic reticulum stress in the hippocampus, we determined the expression of key molecular players involved in PERK, ATF6, and IRE1 branches of the UPR." (PMID 29743975, 2018).
intracerebral hemorrhage (4 papers, 2021 to 2023). A cerebrovascular disorder characterized by bleeding into one or both cerebral hemispheres including the basal ganglia and the cerebral cortex. "For example, melatonin was found to ameliorate neurological function in an intracerebral hemorrhage model, which may be attributable to the downregulation of the apoptotic proteins associated with ATF6 and downstream CHOP." (PMID 36769462, 2023). "The administration of melatonin can significantly decrease the mRNA and protein levels of ATF6 and CHOP in intracerebral hemorrhage rats, indicating that melatonin can protect neurons against apoptosis by suppressing ATF6 and CHOP." (PMID 36768703, 2023). "In the reported assay, usage of the investigated inhibitor appeared to be detrimental to ATF6-knockout medaka, as it induced intracerebral hemorrhage in ATF6α−/− embryos, but not in the wild-type ones." (PMID 33562589, 2021). "Although CDNF was shown to regulate UPR initiated by transducers IRE1α, PERK and ATF6 in the pathological condition, we found that mRNA levels of UPR markers Grp78, spliced Xbp1, Atf4, and Chop were not significantly different between WT and Cdnf−/− mice after intracerebral hemorrhage." (PMID 36792604, 2023).